ACTR5 (actin related protein 5)
Description:
Proposed core component of the chromatin remodeling INO80 complex which is involved in transcriptional regulation, DNA replication and probably DNA repair. Involved in DNA double-strand break repair and UV-damage excision repair.
Synonyms: ARP5; FLJ12785; INO80M
Tractability: Small molecule: a structure with a bound ligand is known. PROTAC: UniProt records ubiquitination sites on it; ubiquitination databases record sites on it; its protein half-life has been measured.
Gene: Protein-coding gene on chromosome 20 (38,748,457 to 38,772,520, forward strand). Ensembl gene ENSG00000101442.
Subcellular location: Nucleus; Cytoplasm
Pathways (Reactome):
DNA Repair: DNA Damage Recognition in GG-NER
Metabolism of proteins: UCH proteinases
Gene Ontology:
Molecular function: protein binding; enzyme regulator activity
Biological process: chromatin remodeling; double-strand break repair; positive regulation of DNA-templated transcription; regulation of cell cycle; regulation of chromosome organization; regulation of DNA replication; regulation of DNA strand elongation; UV-damage excision repair; regulation of DNA-templated transcription; DNA metabolic process; regulation of DNA metabolic process
Cellular component: cytoplasm; Ino80 complex; nucleus; nucleoplasm
Genetic constraint (gnomAD): Loss-of-function variants: 46 observed, 59.63 expected, observed/expected ratio (o/e) 0.77, 90% interval 0.61 to 0.99. The upper end of that interval is the gene's LOEUF score, 0.99, which puts it in group 4 of 6, group 1 being the genes least tolerant of losing a copy. Missense variants: 789 observed, 776.36 expected, observed/expected ratio (o/e) 1.02, 90% interval 0.96 to 1.08. Synonymous variants: 330 observed, 300.27 expected, observed/expected ratio (o/e) 1.1, 90% interval 1 to 1.2.
Homologues: Orthologues: chimpanzee ACTR5 (99% identical), macaque ACTR5 (99% identical), dog ACTR5 (93% identical), pig ACTR5 (93% identical), guinea pig ACTR5 (93% identical), rabbit ACTR5 (93% identical), rat Actr5 (90% identical), mouse Actr5 (89% identical), tropical clawed frog actr5 (65% identical), zebrafish actr5 (54% identical), Drosophila melanogaster Arp5 (36% identical). Paralogues in human: ACTA2 (21% identical), ACTC1 (21% identical), ACTG2 (21% identical), ACTA1 (21% identical), ACTBL2 (21% identical), ACTB (21% identical), ACTG1 (21% identical), ACTR2 (18% identical), ACTR1B (17% identical), ACTR1A (17% identical), ACTL6B (16% identical), ACTL6A (16% identical), and 14 more.
Diseases named in the same sentence as ACTR5 in open-access papers:
ACTR5 is named in the same sentence as 11 diseases in open-access papers, as found by Europe PMC text mining. Sharing a sentence is not in itself a finding about the gene and the disease. The quoted sentences say what the papers report.
Autoimmunity (1 paper, 2025). The occurrence of an immune reaction against the organism's own cells or tissues. "Two de novo variants occurring in genes not previously linked to SLE or autoimmunity, DHX8 and ACTR5, enhanced type I IFN signaling." (PMID 40386946, 2025).
ischemic cardiomyopathy (1 paper, 2023). Ischemic cardiomyopathy is a cardiomyopathy in which a weakness in the muscle of the heart due to inadequate oxygen delivery to the myocardium with coronary artery disease being the most common cause. "Moreover, from the RNA‐seq data of human dilated and ischemic cardiomyopathy, the expression of Tnnt2 and Ttn was significantly negatively correlated with Actr5 expression (r = −0.3369, P = 0.0065 between Tnnt2 and Actr5; r = −0.3847, P = 0.0017 between Ttn and Actr5)." (PMID 36610028, 2023).
lupus (1 paper, 2025). "Of note, two identical twins from proband 47 both carry the novel and de novo variant E424Q in ACTR5, and both twins exhibit a UV-sensitive clinical lupus phenotype." (PMID 40386946, 2025).
neuroblastoma (1 paper, 2024). Neuroblastoma (NB) is the most common solid, extracranial childhood tumor. "ACTR5 has a pro-tumorigenic effect in neuroblastoma, and the knockdown of ACTR5 reduces cell proliferation and differentiation abilities." (PMID 39185313, 2024).
rhabdomyosarcoma (1 paper, 2022). A rare aggressive malignant mesenchymal neoplasm arising from skeletal muscle. "Actin-related protein 5 (Arp5) knockdown increases myogenic gene expression in rhabdomyosarcoma (RMS) cells." (PMID 35348112, 2022).
cancer (3 papers, 2022 to 2024). A tumor composed of atypical neoplastic, often pleomorphic cells that invade other tissues. "In contrast, depletion of the RFP-positive cells in CRISPR-KO sgRNAs targeting ACTR5 (sgACTR5)-transduced cultures was significantly more pronounced in HCC than in other cancer cell types." (PMID 36563143, 2022). "Especially, 7 of ATPCRs showed a significant overexpression in multiple cancer types, including TTF2 (n = 6), RAD54L (n = 4), ACTL6A (n = 4), CHD7 (n = 3), HELLS (n = 3), HLTF (n = 3), and ACTR5 (n = 3)." (PMID 35789070, 2022).
infection (2 papers, 2022 to 2023). The state of being infected such as from the introduction of a foreign agent such as serum, vaccine, antigenic substance or organism. "ARP5‐AAV6 infection increased the expression of the Actr5 gene in hearts by an average of approximately two‐fold compared with the mock AAV6 infection and resulted in a slight, but significant increase in relative heart weight." (PMID 36610028, 2023). "Four weeks post infection, several muscle-related mouse proteins to were up-regulated, such as actin-related protein 5, junctophilin-3, ATP-sensitive inward rectifier potassium channel 11 and tissue-nonspecific alkaline phosphatase." (PMID 35271623, 2022).
tumor (2 papers, 2022). "Together, our results nominated CDKN2A as the cell cycle checkpoint underlying the ACTR5 network to control tumor progression." (PMID 36563143, 2022). "(A) Comparison of ACTR5 expression in normal skeletal muscle, tumor-adjacent skeletal muscle, embryonal RMS (ERMS), and alveolar RMS (ARMS) from published RNA-Seq data (GSE28511)." (PMID 35348112, 2022). "ACTR5/IES6 promotes tumor progression via epigenetic silencing of CDKN2A." (PMID 36563143, 2022). "Here, we used an epigenetics-focused CRISPR interference screen and identified ACTR5 (actin-related protein 5), a component of the INO80 chromatin remodeling complex, to be essential for HCC tumor progression." (PMID 36563143, 2022). "ACTR5 expression was significantly higher in human embryonal and alveolar RMS tissues compared with healthy and tumor-adjacent skeletal muscles." (PMID 35348112, 2022). "Suppression of ACTR5 activated CDKN2A expression, ablated CDK/E2F-driven cell cycle signaling, and attenuated HCC tumor growth." (PMID 36563143, 2022).
ACTR5 also shares sentences with these, for which no sentence is quoted: acute myeloid leukemia (1 paper); breast carcinoma (1); glioblastoma (1).